SNORA16A (small nucleolar RNA, H/ACA box 16A)
Synonyms: ACA16
Gene: Small nucleolar RNA gene on chromosome 1 (28,580,920 to 28,581,056, reverse strand). Ensembl gene ENSG00000274582.
Gene Ontology:
Biological process: RNA processing
Cellular component: nucleolus
Homologues: Orthologues: mouse Snora16a (85% identical).